BRAF (B-Raf proto-oncogene, serine/threonine kinase)
Diseases named in the same sentence as BRAF in open-access papers (continued):
Sharing a sentence is not in itself a finding about the gene and the disease.
tumor (continued). "Interestingly, the mechanism of action of the MEK inhibitor can determine the different efficacy between KRAS- and BRAF-mutant tumours; specifically, MEK inhibition that also blocks feedback reactivation of MEK by wild-type RAS enhanced efficacy in RAS-mutant tumours relative to BRAF-mutant tumours." (PMID 34200676, 2021). "In univariable Cox regression analysis neither baseline characteristics such as the BRAF status or the tumor load at treatment start (LDH/S100) nor the pretreatments and therapy regimes used were significantly influencing PFS with metabolic response as the only significant factor." (PMID 34073477, 2021). "Considering the off-target effects of BRAF/MEKi therapy, such as a paradoxical activation of CD8+ T-cells, it seems conceivable that a longer initial treatment with TT might prime anti-tumor immunity towards a more durable response even after treatment cessation." (PMID 34065877, 2021). "Interestingly, ablation of BRAF did not reproduce this tumour-protective effect, suggesting that it is due to a specific RAF1 function." (PMID 33920182, 2021). "As demonstrated by the pathway enrichment analysis, negative BL samples showed a higher fraction of Tumor Infiltrating Immune Cells (TIICs; absolute score mean of 1.82), similar to what was obtained for BRAF V600E positive samples (absolute score mean of 1.69)." (PMID 34680332, 2021). "Regarding BRAF, tumor sidedness, and LN skip pattern did not affect RFS." (PMID 33484192, 2021). "Plasma circulating tumor DNA (ctDNA) analysis before treatment may allow selection of patients who could benefit, as median OS and PFS were longer in patients with RAS/BRAF WT ctDNA (17.3 vs. 10.4 months, p = 0.02, and 4.1 vs. 3.0 months, p = 0.004, respectively)." (PMID 34944931, 2021). "Moreover, hyperactivation and overexpression of RTKs were described as one of the mechanisms of acquired resistance to BRAF inhibitors through reactivation of key signaling pathways (MAPK, PI3K/AKT) and changes in the cells’ interactions with the tumor microenvironment." (PMID 33918490, 2021). "Interestingly, when mentioned enhancement of oHSV replication with MEKi, it only functions with BRAF V600E-mutated tumor cells, and BRAF wt/RAS-mutated tumor cells, not for BRAF wt/RAS wt tumor cells." (PMID 34578339, 2021). "Additionally, we found that the status of Fusobacteria was associated with the age of the patients, tumor diameter, and MSI status, but not with genetic mutations in KRAS, NRAS, BRAF, and PIK3CA." (PMID 34650531, 2021). "Additionally, it was found that the abundance of Fusobacteria in CRC tumor tissues was associated with MSI status, but not KRAS, NRAS, BRAF, and PIK3CA gene status." (PMID 34650531, 2021). "However, we found no statistically significant concordance in any BRAF, KRAS, NRAS, and TERT promoter mutation between the tumor tissue versus plasma, and the metastatic lymph node versus plasma." (PMID 33915745, 2021). "Second, TGF-β and IL-10, which are closely related to tumor cell invasion, are increased in the exosomes of metastatic small cell lung cancer cells, and this activates SMAD, phosphatidylinositol 3-kinase (PI3K)/AKT, BRAF-MAPK, and other signaling pathways, thereby promoting tumor metastasis." (PMID 34485600, 2021). "We propose that this function may be important for BRAF-mutated tumor cells to suppress p21CIP1 overexpression, which can be triggered by aberrant MEK/ERK activity in these tumor cells if not prevented." (PMID 34947982, 2021). "The tumour mutational profile identified no mutations in the KRAS, NRAS or BRAF genes." (PMID 32899374, 2020).
tumor (continued). "Furthermore, the combination of BRAF and MEK inhibitors (such as dabrafenib and trametinib, or vemurafenib and cobimetinib) improved tumour response rate and progression-free survival, while attenuating some of the serious adverse events observed with monotherapy." (PMID 33216826, 2020). "This tumor is negative for BRAF V600E and calretinin by immunohistochemistry." (PMID 32040459, 2020). "In contrast to BRAF inhibitors, mAbs partly exert their cytotoxic effects by reducing ectodomain density or by inducing receptor-mediated endocytosis through the activation of antibody-dependent cellular cytotoxicity (ADCC) toward tumor cells overexpressing the specific TAA." (PMID 32899183, 2020). "However, this tumor rarely metastasizes to the brain and in one meta-analysis, BRAF status was not related to distant metastasis." (PMID 33042847, 2020). "Therefore, the tumor dataset was filtered to include only those tumors with a documented BRAF fusion, regardless of fusion partner." (PMID 33206716, 2020). "Since our IPM is based on tumor microenvironment-related genes, although its establishment is related to EGFR mutation, ALK translocation, ROS1 translocation, and BRAF mutation, it is applicable to all patients with or without these mutations in stage I-II LUAD." (PMID 33585210, 2020). "Importantly, the more sensitive detection parameters did not result in any false positive calls in non-KIAA1549:BRAF PA or other tumor types (100% specificity)." (PMID 32476062, 2020). "Comparison of γδ T-cell density according to the tumor BRAF and RAS mutational status showed a decrease, although not significant, of γδ T-cell density in tumors harboring BRAF mutations compared with wild type (WT) tumors, whereas it was comparable between WT and RAS mutated samples." (PMID 32599843, 2020). "Moreover, apoptosing tumor cells in patients responding to BRAF inhibitor will not be able to produce Gal‐1, whereas in progressing patients, increasing tumor volume/mass will likely produce more lectin." (PMID 32330348, 2020). "Likewise, BRAF mutation and MSI do not predict tumor recurrence in early stage CRC, while they both are negative prognostic factors in advanced disease." (PMID 30842570, 2019). "In a conditional knock-in mouse model, the BRAF D594A mutant does not drive tumor development per se, but it is able to induce aneuploidy in murine splenocytes and mouse embryonic fibroblasts and contributes to immortalization through the propagation of aneuploid cells." (PMID 31398831, 2019). "Other promising therapeutic strategies in metastatic CM include BRAF/MEK inhibitors with the potential to restore immune system properties by increasing the recruitment of CD8+ T-cells, their infiltration of the tumor and the release of tumor antigens avidly recognized by cytotoxic cells." (PMID 31750245, 2019). "Tumours with somatic mutations such as BRAF, EGFR or gene rearrangements such as ALK are considered therapeutic options regardless of tumour type or location, and tumours may even be characterised as BRAFomas or ALKomas." (PMID 30667539, 2019). "This synthetic lethality will be best leveraged using BRAF inhibitors such as vemurafenib, which specifically inhibit ERK1/2 signalling in BRAFV600-mutant tumour cells, but may also transform the potential of MEKi and ERKi in ERK1/2-addicted melanoma tumour cells." (PMID 31727888, 2019). "While tumor burden and treatment were not predictors of survival in the multivariable model, when correcting for BRAF-status and LDH, subjects with high IL-6 and high IL-8 had a 3.1 times increased risk of death (95% CI, 1.4–14.2) compared to subjects with low IL-6 and low IL-8 (p = 0.012)." (PMID 31781510, 2019). "In addition, the associations of LUNAR1 with sex, age, tumour location, MSI, KRAS mutation, BRAF mutation, and PIK3CA mutation were not statistically significant." (PMID 31882986, 2019).
tumor (continued). "Such an integrated final diagnosis in CNS-JXG neoplasms will allow for refinement of management with tailored treatment protocols and possible expansion of the spectrum of pediatric ECD, based on pathology, molecular and clinical/radiographic correlation in the post-BRAF era." (PMID 31685033, 2019). "However, we were able to establish a negative prognostic value of tumor side irrespective of BRAF status and type of chemotherapy administered as first-line." (PMID 31036005, 2019). "However, whole exome sequencing recently led to the detection of a secondary mutation in mutant BRAF, which confers resistance to RAF inhibitor, in a brain tumour that was progressing though not before the tumour was treated." (PMID 31126017, 2019). "This long-term benefit of targeted therapies may be related to an immune modulation: indeed, BRAF and MEK inhibitors affect tumor microenvironment and immune surveillance, and patients with complete response to targeted treatment have a pre-existing favorable immunologic signature." (PMID 31412885, 2019). "Black patients with MSI tumours occurred in younger patients with left- (36%) and right-sided (59%) tumours, associated with dMSH2/6 (45%), and dMLH1/PMS2 (36%) tumours with a lack of BRAF mutations, indicating a possible LS cause." (PMID 31636305, 2019). "Activation of the second arm of the serrated neoplasia pathway, also driven by CpG island methylation of unspecified tumor-suppressor genes but not DNA-repair genes, may indicate progression to BRAF-mutant MSS carcinoma." (PMID 30458818, 2018). "Fourth, expression of activated BRAF V600E alone does not lead to tumor development in in vitro and in in vivo mouse models, while the combined activation of BRAF and loss of CDKN2A/B is transforming, suggesting that additional mutations to bypass senescence are required to advance to phase III." (PMID 29616301, 2018). "Since the mechanisms by which metabolic alterations interact with signaling downstream from mutated BRAF and KRAS have not been completely elucidated, the aim of our study was to investigate the impact of BRAFV600E and KRASG12V on tumor cell metabolism and signaling." (PMID 29907857, 2018). "The molecular differences in BRAF and NRAS mutations and CIMP-high and gene expression in tumor sidedness may account for this since the effect of primary tumor location was not significant on multivariate analysis." (PMID 30296945, 2018). "However, the AZ304 and Cetuximab combination reversed EGFR activation associated with AZ304, and resulted in stronger anti-tumour activity in vitro and in vivo, in RAS wild type CRC cells irrespective of BRAF genetic status." (PMID 29755114, 2018). "Multivariate Cox proportional hazard analyses incorporating primary tumor anatomic site, type of perioperative chemotherapy, treatment year, or mutational data, including KRAS mutation, BRAF mutation, or MSI, did not independently contribute to prognostication in our cohort." (PMID 29728604, 2018). "Treatment with 5-FU-based regimens improved prognosis in patients with the combination of MSS tumours, KRAS mutation and CIMP negative (log rank P = 0.003) as well as in patients with MSS tumours plus BRAF and KRAS wild-type and CIMP negative (log-rank P<0.001)." (PMID 30188916, 2018). "We have previously demonstrated that the most common BRAF-fusion in PLGGs, KIAA1549-BRAF, has innate resistance to first-generation RAFi vemurafenib (research analog PLX4720), and instead is paradoxically activated upon PLX4720 treatment resulting in accelerated tumor growth." (PMID 29156677, 2017). "Finally, we generated a virtual patient population using published clinical data on BRAF, MEK, and EGFR antagonists, which accurately predicted population level-tumor responses to single agent treatment with the ERKi GDC-0994, and projected strategies to increase the single agent responses." (PMID 28649441, 2017). "The biological correlation pattern between BRAF and KRAS might depend on tumor location." (PMID 28623901, 2017).
tumor (continued). "In contrast, the studies presented here define a role for RhoJ signaling in regulating the growth of BRAF mutant melanocytes at all stages, and result in the remarkable observation that early, limited treatment with PAK inhibitors is effective in halting tumor growth." (PMID 28753606, 2017). "In contrast, two patients (Patients #3 and #4) with WT BRAF exhibited no increase in LDH release in any of the treatment conditions showing that as with our previous studies in cell lines, primary tumor samples with WT BRAF display no significant sensitivity to autophagy inhibition." (PMID 28094001, 2017). "These cells would proliferate as they would have a survival advantage by not being affected by BRAF inhibition, and may account for the presence of an even greater tumor burden in patients who have responded to BRAF inhibition but then develop resistance." (PMID 29100459, 2017). "Nevertheless, mutations in genes like BRCA1, BRAF, and PDGFBA were still detected in the plasma suggesting that tumor cells harboring these mutations were not eliminated by the therapy and that these mutations may actually confer a resistance mechanism." (PMID 28472989, 2017). "Importantly, the presence of these ncRNAs was independent of BRAF-V600E and SMO-L412F mutations, histology type or tumour location, but was positively correlated with the tumour size." (PMID 27965463, 2017). "The absence of identifiable BRAF V600E mutant protein suggest that mutation of BRAF gene is not implicated in the pathogenesis of POT, and may confirm that this tumor does not belong to the category of those BRAF-mutant positive ameloblastic tumors." (PMID 28390134, 2017). "However, if limited to wild-type RAS/BRAF tumours, there were no clear differences in OS among sites of primary lesions." (PMID 28972961, 2017). "Remarkably, tumor vascular invasion could be observed in control tumors with intact BRAF and WIPF1, while, in contrast, no vascular invasion was observed in the tumors with WIPF1 or BRAF knockdown." (PMID 27863429, 2017). "RQI results were compared to patients’ age and sex, tumor site, kind of surgery, anastomosis failure, adenocarcinoma type and grade, tumor cell percentage, necrosis extent, HIF-1α and cleaved caspase-3 immunohistochemistry, and BRAF, KRAS and microsatellites status." (PMID 27124490, 2016). "Therefore BRAF V600mut ctDNA seems to reflect the BRAF V600mut-dependent proliferative tumor burden, and not tumor mass as evidenced by CT-imaging." (PMID 27095081, 2016). "Thus, our data suggest that IL-15 and IL-18 cytokines could be utilized in combination with BRAF/MEK inhibitors to sustain and/or activate NK cell anti-tumor potential in vivo." (PMID 27563819, 2016). "Oncogenic pathways, including KRAS/BRAF that occur in high frequency in colon cancer, circumvent the canonical HH-GLI axis by converging on and further driving GLI to a higher activating state in tumor cells, promoting cellular proliferation, tumor progression and survival." (PMID 27863397, 2016). "Thus, when targeted NGS results were compared to results obtained by real-time PCR for tumor samples from patients with NSCLC, the two methods had high concordance rates for the three genes tested: 96.3% for EGFR, 98.7% for KRAS, and 100% for BRAF." (PMID 27589834, 2016). "An increase in tumor infiltration by CD8+ lymphocytes with a decrease in regulatory T cells (Tregs) and other immunosuppressive cells, as well as an increase in PD ligand (PD-L1) expression on tumor cells, have also been observed in tumors responding to BRAF/MEKi." (PMID 27447748, 2016).
tumor (continued). "Thus, the BRAF V600E mutation is associated with older age and conventional PTC but not more established prognosticators such as tumor size, multifocality, or TNM stage in TERT promoter-negative cases." (PMID 27064992, 2016). "Genomic analysis revealed neither an ALK gene rearrangement nor EGFR, BRAF or HER2 gene mutations, but an activating point mutation of the KRAS gene (p.G12C, exon 2) and therefore this tumor could be considered a non-responder case to EGFR-TKI therapy." (PMID 27548442, 2016). "While 24 of 112 tumor samples showed intermediate-methylation epigenotype significantly correlating with KRAS-mutation(+) (P=3×10-4), 88 tumor samples showed low-methylation epigenotype correlating with the absence of KRAS- and BRAF-mutations." (PMID 27563825, 2016). "It has been reported that BRAF inhibitors block the MAP kinase signaling pathway in BRAFV600E cells, whereas in BRAFWT tumors, BRAFi activates the RAF-MEK-ERK pathway and could enhance tumor growth in xenograft models." (PMID 26943572, 2016). "Similarly, the down-regulated miR-7-2-3p, miR-138-3, miR-138-5p, miR-139-5p, miR-152-3p, miR-204-5p, miR-652-3p, miR-873-5p and miR-1179 show decreased expression in BRAF V600E positive tumor samples compared to BRAF V600E negative tumor samples." (PMID 27248468, 2016). "This could simply be explained by assuming that the particular tumor fragment from which this PDX was derived did not contain the BRAF amplification." (PMID 26105199, 2015). "Patients with tumours <= 10 mm were over-represented among BRAF negative population (p=0.03)." (PMID 26177218, 2015). "The mutation rate of other oncogenes was not significantly different between the LGSCs and SBTs; however there was a trend towards a lower frequency of BRAF and KRAS mutants in the LGSCs and a higher rate of “wildtype” tumours, where no oncogenic mutation was identified." (PMID 26506417, 2015). "The fact that oncogenic BRAF signaling induces a feedback inhibitor of transformation indicates that a fine balance between promoting and inhibiting forces are required for optimal transformation, or that the induction of MIG-6 is a remnant of its original function as a tumor suppressor." (PMID 26065894, 2015). "While no comprehensive data on secreted factors determined by KRAS or BRAF oncogenes are available in CRC, this might comprise a further molecular level of specificity determining both the distinct roles of KRAS and BRAF in tumor progression and therapy response." (PMID 26299805, 2015). "The result of this work demonstrated that CI did not have anti-tumor activity in BRAF mutant CRC." (PMID 26486455, 2015). "The KM curves, which are unadjusted for other prognostic factors, suggest that patients receiving a BRAF inhibitor after diagnosis of brain metastases had better survival outcomes than patients with BRAF mutant tumours who did not receive this treatment (log-rank test P=0.029)." (PMID 26484413, 2015). "This means that at least 78% (7/9 patients) MSI-High lesions detected with the LMR panel were LS (based on germline MMR mutations) or probable LS (based MSI-High tumor phenotype, loss of MMR expression by IHC, lack of BRAF V600E mutation, early age of onset and cancer history)." (PMID 26252492, 2015). "With regard to molecular tumor characteristics, MT1-MMP expression did neither correlate with the presence of an activating KRAS or BRAF mutation nor correlate with MMR protein expression at the leading edge of the examined tumors in our sample set (P = 0.812, 1.0, and 0.471, resp)." (PMID 26106602, 2015). "Together, the lower mitotic index, the lower MAPK activation, and the more circumscribed tumor borders may explain the lack of symptoms observed in these mice at 12 weeks post-injection as compared to BRAF-FLVE-induced tumors." (PMID 25821557, 2015).